APOE (apolipoprotein E)
Diseases named in the same sentence as APOE in open-access papers (continued):
Sharing a sentence is not in itself a finding about the gene and the disease.
atherosclerosis (continued). "Furthermore, irisin treatment significantly ameliorated atherosclerosis in ApoE-deficient mice fed on high cholesterol diet and reduced inflammation of the aortic tissue." (PMID 33597894, 2021). "In relation to cardiovascular disorders, the role of a powder of the microalga Dunaliella bardawil, containing 6% β-carotene isomers, was examined in a model of atherosclerosis in apolipoprotein E (apo E)-deficient mice, and fed with a vitamin A-deficient diet." (PMID 34677429, 2021). "Apolipoprotein E (ApoE) is a major apolipoprotein for the regulation of lipid and cholesterol metabolism in central nervous system (CNS; Mahley, 1988), and has been associated with physiopathology of Alzheimer's and atherosclerosis." (PMID 34423582, 2021). "Allelic variation at the APOE locus impacts survival by both altering the age at onset of AD and by increasing risk of other conditions (hyperlipidaemia, atherosclerosis, cardiovascular disease), and the frequency of APOE-ε4 in the population correspondingly goes down with age11." (PMID 34301930, 2021). "Recently, a VSMC-lineage tracing study on apoE-deficient mice fed a high fat diet showed that dedifferentiated Sca1+ VSMCs located near the necrotic core could promote atherosclerosis by evading macrophage efferocytosis." (PMID 34572399, 2021). "T cells from atherosclerosis-prone Apolipoprotein E deficient (Apoe−/−) mice secrete IFN-γ." (PMID 33669769, 2021). "Thus, in the present study, we aimed to investigate the effects of AceK on the development of atherosclerosis in apolipoprotein E deficient (ApoE−/−) mice." (PMID 34836239, 2021). "Apolipoprotein E deficient (ApoE−/−) mice are highly vulnerable to atherosclerosis." (PMID 35295127, 2021). "In turn, GAS5 knockout resulted in decreased progression of atherosclerosis in apoE-deficient mice." (PMID 33922114, 2021). "While apoE2 and apoE4 are both pro-inflammatory in myeloid cells and apoE2- and apoE4-expressing bone marrow cells are pro-atherogenic, the underlying mechanisms by which these apoE isoforms enhance inflammation and atherosclerosis are quite different." (PMID 34425108, 2021). "APOE gene polymorphisms have been shown to be associated with atherosclerosis." (PMID 32891149, 2020). "Human apolipoprotein-E (ApoE) is a polymorphic multifunctional protein with isoforms of ApoE2, ApoE3, and ApoE4, and is strongly implicated in two major inflammatory diseases, AD and atherosclerosis." (PMID 32069870, 2020). "Increased atherosclerosis was observed when NK cells were transferred into ApoE(-/-)Rag2(-/-)IL2rγ(-/-) mice, whereas decreased atherosclerotic lesions were found in NK cell depleted ApoE(-/-) or when GrB/perforin-deficient NK cells were transferred." (PMID 33262766, 2020). "Apolipoprotein-E (ApoE) is strongly associated with atherosclerosis and Alzheimer’s disease (AD)." (PMID 32069870, 2020). "Moreover, the level of this miRNA was reduced in the aorta of apoE-/- mice in comparison to controls, highlighting its important role in the regulation of atherosclerosis-associated processes." (PMID 32155866, 2020). "Furthermore, one experimental study demonstrated that inhibition of galectin-3 reduces atherosclerosis in apolipoprotein E-deficient mice, suggesting that galectin-3 plays a critical role in the development of atherosclerosis." (PMID 33195327, 2020). "APOE ε4 allele carriage was related to higher risks of atherosclerosis." (PMID 31919381, 2020). "The ApoE-deficient mouse is an established murine model for human atherosclerosis." (PMID 32075280, 2020). "Upregulating Nrf2 signaling may reduce the risk of atherosclerosis, and we therefore speculate and examine whether JC-5411 has the potential to decrease atherosclerotic lesions in ApoE−/− mice." (PMID 33442380, 2020).
atherosclerosis (continued). "Another study conducted in apoE-/- and in apoE-/- and PKCβ-/- double knock-out mice with chemically induced diabetes showed that increased PKCβ activation was linked to accelerated atherosclerosis development through the induction of CD11c and pro-inflammatory activation of macrophages." (PMID 32155866, 2020). "Similarly, the finding that ApoE-knockout mice deficient in TLR-4 have less atherosclerotic burden also supports the notion of a role of metabolic endotoxemia in atherosclerosis." (PMID 33505393, 2020). "However, a recent study in APOE*3-Leiden.CETP mice showed that intravenous inoculation of M. bovis BCG was associated with decreased atherosclerosis formation in the aortic root after 6 weeks of infection." (PMID 33391278, 2020). "We previously reported that high concentrations of uric acid synthesis metabolites lead to the generation of reactive oxygen species (ROS), which promotes hypercholesterolemia with cholesterol accumulation in hepatocytes and incites atherosclerosis in apolipoprotein E (ApoE)-deficient mice." (PMID 33050202, 2020). "First, a previous study indicated that the decreased atherosclerosis development may be associated with the inhibition of Th17-associated cytokines in the spleen in ApoE KO mice." (PMID 32911750, 2020). "Apolipoprotein E (ApoE) polymorphism and adipokines are linked to atherosclerosis." (PMID 33297350, 2020). "Mice that are ApoE deficient (ApoE−/−) are commonly used as an animal model for atherosclerosis." (PMID 33343375, 2020). "In the apolipoprotein E-deficient (ApoE61/61) mouse model, the administration of recombinant mouse sclerostin protein, an inhibitor of the Wnt signaling pathway, inhibited angiotensin II-induced atherosclerosis." (PMID 32138681, 2020). "CD36 deficiency in ApoE−/− mice can inhibit neointimal hyperplasia and vascular smooth muscle cells (VSMCs) proliferation, which may prevent atherosclerosis and restenosis." (PMID 33371312, 2020). "Moreover, galectin-3 deficiency, in a mice model of atherosclerosis (ApoE−/−), decreased plaque size, its necrotic core, and collagen content, which was consistent with our findings." (PMID 33238643, 2020). "Deletion of the Gpx1 in atherosclerosis-prone apolipoprotein E-deficient (ApoE−/−) mice caused accelerated atherosclerotic plaque formation and enhanced vascular oxidative stress, whereas Gpx1 deficiency in wildtype mice resulted in more pronounced aging-associated complications." (PMID 32408480, 2020). "Moreover, an overproduction of HA in the genetic background of the apoE-deficient mouse strain promotes atherosclerosis development in the aorta." (PMID 31932306, 2020). "Importantly, the effects observed in the APOE*3Leiden.CETP mice confirm that icosabutate significantly inhibits the development of atherosclerosis in association with reductions in atherogenic plasma lipids." (PMID 32841505, 2020). "In particular, apoprotein E (ApoE) is a polymorphic protein whose primary functions are to transport lipids and to participate in lipoprotein and cholesterol metabolism; it has been reported as a risk factor for both atherosclerosis and AD." (PMID 33121058, 2020). "tBHQ was reported to ameliorate diabetes‐driven atherosclerosis in apolipoprotein E‐deficient mice." (PMID 32628815, 2020). "However, later studies provided evidence that increased expression of TRPC6 due to a reduction in miR-26a in ApoE−/− mice fed an atherogenic diet was associated with more advanced atherosclerosis." (PMID 32872338, 2020). "A study by M. Ditiatkovski and coworkers shows that, in apoE-deficient mice, the volume of atherosclerotic damage and macrophage accumulation increases if GM-CSF is downregulated, suggesting that, in vivo, GM-CSF protects from atherosclerosis." (PMID 32823638, 2020).
atherosclerosis (continued). "Thus, dietary NAM supplementation in ApoE-deficient mice prevented the development of atherosclerosis and improved protection against ApoB-containing lipoprotein oxidation and aortic inflammation." (PMID 33233455, 2020). "Moreover, a recent study using Has3/ApoE double deficient mice clearly demonstrated that Has3-mediated HA synthesis was critical in the development of atherosclerosis." (PMID 33171800, 2020). "In this study we utilized apolipoprotein E-deficient (ApoE−/−) atherosclerosis mouse models to explore whether JC-5411 (PEITC formulation) has anti-atherosclerosis activity in vivo, and to ascertain the underlying mechanism of its action." (PMID 33442380, 2020). "In the current study, TFA reduced atherosclerosis and enhanced plaque stability in apoE deficient mice, which may be attributed to the improvement of lipid metabolism and inhibition of inflammation in liver and macrophage." (PMID 33381046, 2020). "In addition, treatment with the serine palmitoyltransferase inhibitor myriocin reversed endothelial dysfunction and atherosclerosis in streptozotocin-treated and in apolipoprotein E (ApoE)-deficient mice." (PMID 32564139, 2020). "It has been demonstrated that RBP4 expression was enhanced in the areas rich in macrophage foam cells in atherosclerotic lesions of aortic specimens from both humans and apolipoprotein E-deficient mice, suggesting foam cell-like formation in our biomimetic atherosclerosis models." (PMID 32947976, 2020). "Ex vivo near-infrared fluorescence and confocal fluorescence microscopy revealed multiple fluorescent hotspots at atherosclerosis predilection sites, as well as clear colocalization with macrophages and apoptotic cells in ApoE-deficient mice after administration of A5-mNP." (PMID 32106607, 2020). "PEMT deficiency in ApoE−/− mice decreases the PC biosynthesis and attenuates atherosclerosis." (PMID 31379582, 2019). "Interestingly, it was shown that low-grade inflammation driven by LPS aggravates atherosclerosis in an apolipoprotein E-deficient animal model." (PMID 31565149, 2019). "Indeed, while leptin deficiency has been shown to protect apolipoprotein-E-deficient mice fed an atherogenic diet from the development of atherosclerosis lesions, exogenous leptin significantly increases atherosclerotic areas in apoE-deficient mice." (PMID 31656583, 2019). "The role of Bdkrb2 in atherosclerosis was studied in ApoE-deficient mice, which were either Bdkrb2-deficient, or had moderately increased aortic B2 bradykinin receptor protein levels induced by transgenic BDKRB2 expression under control of the ubiquitous CMV promoter." (PMID 30847343, 2019). "Additionally, g-apoA-IV enhanced the development of atherosclerotic lesion in apoE deficient mice that are prone to atherosclerosis." (PMID 30959835, 2019). "Moreover, NOX4 is also considered protective of diabetes-associated atherosclerosis in ApoE KO mice with STZ-induced diabetes." (PMID 31382355, 2019). "Furthermore, a meta-analysis showed a linear relationship between ApoE genotypes and coronary risk, emphasizing the importance of ApoE gene variation for atherosclerosis development." (PMID 31386691, 2019). "Moreover, NOD1 deficiency in ApoE-knockout mice showed reduced development of atherosclerotic lesions from the early stage and delayed progression of atherosclerosis." (PMID 31582899, 2019). "Next, we assessed whether the progression of atherosclerosis and plaque instability observed in ApoE−/− mice deleted for Atg7 in VSMCs was associated with dysfunctional and impaired mitochondrial quality control." (PMID 30741928, 2019). "The key role of TGF-β in maintaining DCs tolerogenicity was demonstrated by knocking out a TGF-β receptor, TGFBR2, in CD11+ DCs, which led to the formation of pro-inflammatory and pro-atherogenic CD11+CD8+ cells and the accelerated progression of atherosclerosis in apoE-deficient mice." (PMID 31717832, 2019).
atherosclerosis (continued). "Gene silencing of NLRP3 suppresses atherosclerosis and stabilizes plaques in ApoE-deficient mice." (PMID 31582899, 2019). "The ApoE-deficient mouse is considered a translational model of human atherosclerosis." (PMID 31575906, 2019). "In addition, decreased ADAMTS-5 expression was found in atherosclerosis of apolipoprotein E (ApoE) null mice, associated with the accumulation of aggrecan and versican." (PMID 31929842, 2019). "Data linking IL-1β to atherosclerosis stem from early work demonstrated that a lack of IL-1β decreases the severity of atherosclerosis and that administration of a monoclonal antibody targeted against IL-1β limits the progression of atherosclerosis in ApoE deficient mice." (PMID 31357404, 2019). "Systemic apoE deficiency leads to atherosclerosis in humans and in animal models." (PMID 30909560, 2019). "Extensive research was carried out on apoE, as a result of two major discoveries related to two dreadful pathologies of the modern developed societies: (i) apoE deficient mice (APOE−/−) spontaneously develop atherosclerosis and (ii) APOE4 allele is a genetic risk factor for Alzheimer’s disease." (PMID 31779116, 2019). "Therefore, our aim in this study was to investigate the potential effect of lubiprostone on impaired intestinal dysfunction and the development of atherosclerosis in apolipoprotein E-deficient (ApoE-/-) mice." (PMID 31206525, 2019). "It is plausible to postulate that the association of plasma ApoE with NAFLD as shown in this report could influence the alleged effect of NAFLD on atherosclerosis susceptibility." (PMID 31386691, 2019). "Of note, it is shown that vascular damage is associated with worsening of neointimal formation in adiponectin-deficient mice, while adiponectin overexpression is shown to lead to inhibition of atherosclerosis in ApoE-deficient mice, which are known to serve as a mouse model of atherosclerosis." (PMID 31475160, 2019). "Moreover, less cholesterol accumulation was observed in the macrophages of atherosclerosis-prone apolipoprotein E-deficient (ApoE‒/‒) mice who underwent Akt1‒/‒ bone marrow transplantation when exposed to modified lipoproteins." (PMID 31635197, 2019). "Further studies are needed to provide more in-depth information on the impact of dietary changes upon lipid clearance and how this might lead to an increased susceptibility to atherosclerosis in apoE deficient rats." (PMID 31796798, 2019). "Apolipoprotein E (apoE) deficient rats have been proposed as animal model of atherosclerosis." (PMID 31796798, 2019). "In addition, MCP-1 deficiency was reported to suppress the progression of atherosclerosis in ApoE-KO mice." (PMID 30858489, 2019). "There are preclinical data from an ApoE deficient murine model suggesting that high dose polyclonal IgG reduces atherosclerosis; therefore, it is plausible that individuals with low serum IgG may be more likely to display dyslipidemia." (PMID 31888499, 2019). "Currently, it is unclear whether there is an independent relationship between atherosclerosis and AD or whether this is primarily due to their shared association with APOE genotype." (PMID 31083442, 2019). "In this study, we demonstrated that bosentan may be an effective treatment in patients with atherosclerosis, particularly as this drug led to major reductions in the atherosclerosis plaques of ApoE-deficient mice in vivo." (PMID 31886257, 2019). "Whereas apoE deficient rats have been proposed as animal model of atherosclerosis, to date it is unknown whether they also develop pronounced ISR." (PMID 31796798, 2019). "Studies using hyperhomocysteinemic apolipoprotein E (apoE) -deficient mice (an animal model of atherosclerosis) also revealed the activation of NF-κB and downstream proinflammatory mediators in atherosclerotic lesions, supporting the role of inflammation in HHcy-associated atherogenesis." (PMID 30781581, 2019).
atherosclerosis (continued). "In aged apolipoprotein E-deficient mice, a model for atherosclerosis, IL-10+ B lineage cells, many of them exhibiting an CD138+ plasma cell phenotype, have been also found within artery tertiary lymphoid organs, i.e., atherosclerosis-associated lymphoid aggregates surrounding the affected arteries." (PMID 31214168, 2019). "In the present study, we explored the role of chemerin in initiation and progression of atherosclerosis in apolipoprotein-E deficient (ApoE−/−) mice to better understand its duty and the underlying mechanism in atherosclerosis and other cardiovascular diseases." (PMID 31781638, 2019). "APOE genotype may play a role in determining AD risk in individuals with atherosclerosis, as the presence of the APOE4 allele appears to strengthen the association with AD." (PMID 31083442, 2019). "After 16 weeks, they found that the ApoE−/−Ppia−/− mice developed significantly reduced atherosclerosis compared with ApoE−/− mice, and CyPA deficiency was associated with decreased vascular cell adhesion molecule 1 (VCAM-1) expression, ROS, inflammation, ECs activation and apoptosis." (PMID 31825469, 2019). "Moreover, we studied the effects of chronic legumain infusion on the development of atherosclerosis in apolipoprotein E-deficient (Apoe−/−) mice, an established animal model of atherosclerosis." (PMID 31060209, 2019). "The aim of the current study is to characterize the interleukin 25 (IL25)-induced splenic ILC2 population (Lin−CD45+IL17RB+ICOS+IL7raintermediate) and address its direct role in experimental atherosclerosis by its adoptive transfer to hypercholesterolaemic apolipoprotein E deficient (apoE−/−) mice." (PMID 31823769, 2019). "APOE protein encoded by the APOE gene, is involved in lipid metabolism and is a well-established risk factor for Alzheimer’s disease and various other aging disorders such as cardiovascular disease, atherosclerosis, stroke and impaired cognitive function." (PMID 31861518, 2019). "The loss of cells in NP tissues of APOE-knockout rabbits by about 42% could be due to the obstructed nutrient transport mediated by atherosclerosis in the abdominal aorta and the lumbar arteries." (PMID 31751427, 2019). "Overexpression of Sirt1 in the endothelium in ApoE-deficient (ApoE−/−) mice induces the expression of eNOS, represses the expression of adhesion molecules, and subsequently inhibits the progression of atherosclerosis." (PMID 31387590, 2019). "We have also shown that the expression of a disintegrin and metalloproteinase with thrombospondin motifs-4 in human macrophages was inhibited by IL-3313, and recently it has been demonstrated that its deficiency in ApoE−/− mice attenuates atherosclerosis development and improves plaque stability." (PMID 31383884, 2019). "In apolipoprotein E-deficient mice and cells, hypoxanthine also induces cholesterol accumulation and stimulates atherosclerosis through alterations in lipid transport enzymes, independent of conversion to xanthine and uric acid, a known risk for cardiovascular disease." (PMID 30883584, 2019). "However, the same group also linked the deletion of the AMPKα1 subunit (on the ApoE-/- background) with increased atherosclerotic calcification, but decreased atherosclerosis via altered macrophage differentiation." (PMID 31248224, 2019). "Thus, reduced atherosclerosis was seen in the Apolipoprotein E deficient (ApoE−/−) mouse model system following administration of recombinant IL-339." (PMID 31383884, 2019). "However, in in vivo studies, the route of LPS injection is limited to intravenous or intraperitoneal, and the doses of LPS usually range between 0.5 mg/kg and 2.5 mg/kg BW, which is sufficient to cause atherosclerosis in apoE-deficient mice." (PMID 29584779, 2018).